ZNF441 (zinc finger protein 441)
Description:
May be involved in transcriptional regulation.
Synonyms: FLJ38637
Tractability: PROTAC: ubiquitination databases record sites on it.
Gene: Protein-coding gene on chromosome 19 (11,767,000 to 11,784,078, forward strand). Ensembl gene ENSG00000197044.
Subcellular location: Nucleus
Subcellular location (Human Protein Atlas): Nuclear speckles
Pathways (Reactome):
Gene expression (Transcription): Generic Transcription Pathway
Gene Ontology:
Molecular function: protein binding; DNA-binding transcription factor activity, RNA polymerase II-specific; RNA polymerase II transcription regulatory region sequence-specific DNA binding
Biological process: regulation of transcription by RNA polymerase II; regulation of DNA-templated transcription
Cellular component: nucleus
Genetic constraint (gnomAD): Loss-of-function variants: 19 observed, 58.56 expected, observed/expected ratio (o/e) 0.32, 90% interval 0.22 to 0.48. The upper end of that interval is the gene's LOEUF score, 0.48, which puts it in group 2 of 6, group 1 being the genes least tolerant of losing a copy. Missense variants: 652 observed, 825.59 expected, observed/expected ratio (o/e) 0.79, 90% interval 0.74 to 0.84. Synonymous variants: 248 observed, 266.62 expected, observed/expected ratio (o/e) 0.93, 90% interval 0.84 to 1.03.
Homologues: Orthologues: chimpanzee ZNF441 (99% identical), macaque ZNF627 (96% identical), mouse Zfp961 (28% identical), rat Zfp617 (28% identical). Paralogues in human: ZNF443 (58% identical), ZNF799 (56% identical), ZNF44 (55% identical), ZNF823 (55% identical), ZNF442 (51% identical), ZNF709 (47% identical), ZNF700 (47% identical), ZNF433 (47% identical), ZNF791 (46% identical), ZNF14 (46% identical), ZNF563 (42% identical), ZNF878 (40% identical), and 3 more.
Diseases named in the same sentence as ZNF441 in open-access papers:
ZNF441 is named in the same sentence as 2 diseases in open-access papers, as found by Europe PMC text mining. Sharing a sentence is not in itself a finding about the gene and the disease. The quoted sentences say what the papers report.
cancer (1 paper, 2025). A tumor composed of atypical neoplastic, often pleomorphic cells that invade other tissues. "Among the identified genes in mild, ZNF441 stood out as a transcription factor involved in multiple infectious contexts, including the regulation of herpes simplex virus (HSV) and cancer progression." (PMID 41417796, 2025).
ZNF441 also shares sentences with these, for which no sentence is quoted: tumour (1 paper).